TP53BP1 (tumor protein p53 binding protein 1)
Description:
Double-strand break (DSB) repair protein involved in response to DNA damage, telomere dynamics and class-switch recombination (CSR) during antibody genesis. Plays a key role in the repair of double-strand DNA breaks (DSBs) in response to DNA damage by promoting non-homologous end joining (NHEJ)-mediated repair of DSBs and specifically counteracting the function of the homologous recombination (HR) repair protein BRCA1. In response to DSBs, phosphorylation by ATM promotes interaction with RIF1 and dissociation from NUDT16L1/TIRR, leading to recruitment to DSBs sites. Recruited to DSBs sites by recognizing and binding histone H2A monoubiquitinated at 'Lys-15' (H2AK15Ub) and histone H4 dimethylated at 'Lys-20' (H4K20me2), two histone marks that are present at DSBs sites. Required for immunoglobulin class-switch recombination (CSR) during antibody genesis, a process that involves the generation of DNA DSBs. Participates in the repair and the orientation of the broken DNA ends during CSR (By similarity). In contrast, it is not required for classic NHEJ and V(D)J recombination (By similarity). Promotes NHEJ of dysfunctional telomeres via interaction with PAXIP1.
Synonyms: 53BP1; p53BP1; p202; TDRD30
Tractability: Small molecule: a structure with a bound ligand is known; a high-quality ligand is known. PROTAC: UniProt records ubiquitination sites on it; ubiquitination databases record sites on it; its protein half-life has been measured; a small molecule that binds it is known.
Target class: Methyl-lysine/arginine binding protein; Reader; Epigenetic regulator; Tudor domain
Gene: Protein-coding gene on chromosome 15 (43,403,061 to 43,510,728, reverse strand). Ensembl gene ENSG00000067369.
Subcellular location: Nucleus; Chromosome; Chromosome, centromere, kinetochore
Subcellular location (Human Protein Atlas): Nuclear bodies; Nucleoplasm
Pathways (Reactome):
DNA Repair: Nonhomologous End-Joining (NHEJ); Processing of DNA double-strand break ends; Recruitment and ATM-mediated phosphorylation of repair and signaling proteins at DNA double strand breaks
Cell Cycle: G2/M DNA damage checkpoint
Metabolism of proteins: SUMOylation of transcription factors
Gene Ontology:
Molecular function: histone H4K20me2 reader activity; histone reader activity; protein binding; RNA polymerase II-specific DNA-binding transcription factor binding; transcription coactivator activity; transcription coregulator activity; ubiquitin-modified histone reader activity; histone binding; damaged DNA binding; histone H4K20me methyltransferase activity; sequence-specific DNA binding; telomeric DNA binding
Biological process: DNA damage response; double-strand break repair via classical nonhomologous end joining; double-strand break repair via nonhomologous end joining; negative regulation of double-strand break repair via homologous recombination; positive regulation of isotype switching; positive regulation of transcription by RNA polymerase II; protein homooligomerization; protein localization to site of double-strand break; DNA damage checkpoint signaling; positive regulation of DNA-templated transcription; chromatin organization; chromatin remodeling
Cellular component: chromosome; chromosome, telomeric region; cytoplasm; nuclear body; nucleoplasm; nucleus; site of double-strand break; DNA repair complex; kinetochore; replication fork
Genetic constraint (gnomAD): Loss-of-function variants: 56 observed, 192.24 expected, observed/expected ratio (o/e) 0.29, 90% interval 0.23 to 0.36. The upper end of that interval is the gene's LOEUF score, 0.36, which puts it in group 1 of 6, group 1 being the genes least tolerant of losing a copy. Missense variants: 2,033 observed, 2,391.8 expected, observed/expected ratio (o/e) 0.85, 90% interval 0.82 to 0.88. Synonymous variants: 786 observed, 859.35 expected, observed/expected ratio (o/e) 0.91, 90% interval 0.86 to 0.97.
Homologues: Orthologues: chimpanzee TP53BP1 (99% identical), macaque TP53BP1 (97% identical), dog TP53BP1 (87% identical), pig TP53BP1 (87% identical), rabbit TP53BP1 (87% identical), rat Tp53bp1 (82% identical), mouse Trp53bp1 (81% identical), tropical clawed frog tp53bp1 (46% identical), zebrafish tp53bp1 (30% identical), Caenorhabditis elegans hsr-9 (13% identical).
Diseases named in the same sentence as TP53BP1 in open-access papers:
TP53BP1 is named in the same sentence as 158 diseases in open-access papers, as found by Europe PMC text mining. Sharing a sentence is not in itself a finding about the gene and the disease. The quoted sentences say what the papers report.
breast cancer (90 papers, 2005 to 2025). A primary or metastatic malignant neoplasm involving the breast. "For example, mutations affecting SOX5 and TP53BP1 can both promote proliferation in breast cancers through very different mechanisms." (PMID 39975330, 2025). "Among PDXs from patients with germline BRCA1/2-mutated breast cancer, 2 of 9 PARPi-resistant models had somatic mutations in TP53BP1 and exposure to olaparib in PDX models correlated with reduced mRNA expression of SHLD1 and SHLD2." (PMID 37430137, 2023). "Low expression of TP53BP1 is associated with increased local recurrence in breast cancer patients treated with conserving surgery and radiotherapy." (PMID 33987091, 2021). "In general, the loss of TP53BP1 is associated with a worse prognosis in breast cancer and consequently TP53BP1 is considered as a tumor suppressor." (PMID 32456160, 2020). "Germline mutations in DNA mismatch repair genes (BRCA1, BRCA2, CHEK2, ERCC4, FAAP100, and TP53BP1, amongst others) are associated with breast cancer susceptibility." (PMID 27608040, 2016). "TP53BP1 may be associated with breast cancer staging and breast cancer prognosis." (PMID 38091511, 2022). "One patient with PARPi-resistant BRCA-mutant breast cancer, identified through genomic analysis of a breast cancer cohort, was found to have biallelic inactivation of TP53BP1." (PMID 32722408, 2020). "In summary, 1,25(OH)2D may protect against breast cancer by activating its receptor and inactivating the CTSL-mediated degradation of TP53BP1 in A-type lamin-deficient cells, which display BRCA1 deficiency, including cells with lost BRCA1." (PMID 32456160, 2020). "Moreover, loss of 53BP1 has also been observed in patient-derived tumor xenograft (PDX) models with acquired resistance to PARPis, and mutations in TP53BP1 have been reported in tumor biopsies from patients with metastatic BRCA1-associated breast cancer receiving platinum chemotherapy or PARPis." (PMID 37209095, 2023). "Forced expression of TP53BP1 in breast cancer cell lines led to upregulation of miR-200b and miR-429, downregulation of ZEB1, and an epithelial-like phenotype, while silencing of TP53BP1 had the opposite effects." (PMID 34884985, 2021). "Breast cancer-related genes from GAD were also identified as ESR1 interactors, including TP53BP1, SRA1, and BBS4." (PMID 33987091, 2021). "Therefore, some breast cancer cases carry a triple biomarker signature—the levels of nuclear VDR, CTSL and TP53BP1 that may be exploited in projecting a treatment strategy in TNBC cases." (PMID 32456160, 2020).
lung carcinoma (24 papers, 2012 to 2026). "As a result (ORF1F2 = 2.56/2.58*2.92 = 0.34), the multiplicative interaction between TERT rs2736100 and TP53BP1 rs560191 in relation to lung cancer risk was statistically significant (OR for interaction = 0.34, 95% CI = 0.14–0.84)." (PMID 33906323, 2021). "There was a significant multiplicative interaction between the OBFC1 rs11191865 and TP53BP1 rs560191 in relation to lung cancer risk (OR for interaction = 2.44 (1.67/0.50*1.37), 95% CI = 1.02–5.87)." (PMID 33906323, 2021). "The GG genotype of TP53BP1 rs560191 was significantly associated with a decreased risk of lung cancer, as compared with the CC genotype (OR = 0.46, 95% CI = 0.29–0.74)." (PMID 33906323, 2021). "Subjects with at least one C allele of TP53BP1 rs560191 had a significant 2-fold increased risk of lung cancer compared with those with at least one C allele of TERC rs1881984 and the GG genotype of TP53BP1 rs560191." (PMID 33906323, 2021). "On the other hand, subjects with the GG genotype of OBFC1 rs11191865 and the GG genotype of TP53BP1 rs560191 were unexpectedly at lower risk of lung cancer than the reference group (OR = 0.50, 95% CI = 0.22–1.11)." (PMID 33906323, 2021). "Previous GWAS suggests that the SNPs in this locus may interact with TP53BP1 to influence lung cancer susceptibility due to the importance of this gene in carcinogenesis." (PMID 37058478, 2023). "TP53BP1 rs560191 may predispose to lung cancer risk depending on the genotypes of either TERT rs2736100 or OBFC1 rs11191865." (PMID 33906323, 2021). "Our findings indicate that TP53BP1 rs560191 may predispose to lung cancer risk depending on the genotypes of telomere-related polymorphisms." (PMID 33906323, 2021). "TP53BP1 is a key regulator in response to IR in other tumor entities such as glioma stem cells, lung cancer cells and PDAC cells." (PMID 39846632, 2024). "In individuals with the GG genotype of TP53BP1 rs560191, the TT genotype of TERT rs2736100 was significantly associated with an increased risk of lung cancer, compared with the TG and GG genotypes combined after adjustment for potential covariates (OR = 2.58, 95% CI = 1.12–5.94)." (PMID 33906323, 2021). "As compared with the reference (at least one G allele of TERT rs2736100 and the GG genotype of TP53BP1 rs560191), lung cancer risk was approximately similar among subjects regardless of combination with TERT rs2736100 and TP53BP1 rs560191." (PMID 33906323, 2021). "Lung cancer risk was approximately similar among subjects regardless of combination with TERT rs2736100 and TP53BP1 rs560191." (PMID 33906323, 2021).
cervical carcinoma (13 papers, 2012 to 2025). A carcinoma arising from either the exocervical squamous epithelium or the endocervical glandular epithelium. "Expression levels of MCM9 and TP53BP1, when higher than the mean expression level, were significantly associated with a poorer outcome for cervical cancer patients if they were HPV18+, yet not HPV16+." (PMID 32066835, 2020). "TP53BP1, MCM9 (at higher than mean levels), POLR2F and SIRT6 (at lower than mean levels), were associated with an increase in patients experiencing cervical cancer recurrence/progression following postoperative radiation therapy when HPV18 positive, but not HPV16 positive." (PMID 32066835, 2020). "Moreover, increased expression levels of TP53BP1 and MCM9 and decreased expression levels of POLR2F and SIRT6 were found to be specifically associated with a poorer prognosis for HPV18+ (but not HPV16+) cervical cancer patients following PRT." (PMID 32066835, 2020).
colorectal cancer (12 papers, 2015 to 2025). A primary or metastatic malignant neoplasm that affects the colon or rectum. "The functions of TP53BP1 in chromatin stability determines its critical role in cancer and reports emergence in breast, lung, prostate and colorectal cancer 23-27." (PMID 32922534, 2020).
ovarian carcinoma (12 papers, 2012 to 2025). A malignant neoplasm originating from the surface ovarian epithelium. "Indeed, overexpression of TP53BP1 has been demonstrated to decrease the clonogenicity and induce apoptosis in ovarian cancer cells." (PMID 25045661, 2014).
triple-negative breast carcinoma (12 papers, 2013 to 2025). An invasive breast carcinoma which is negative for expression of estrogen receptor (ER), progesterone receptor (PR), and human epidermal growth factor receptor 2 (HER2). "It was demonstrated that TP53BP1 is downregulated in most cases of triple-negative breast cancer." (PMID 29504908, 2018).
Fanconi anemia (6 papers, 2016 to 2024). Fanconi anemia (FA) is a hereditary DNA repair disorder characterized by progressive pancytopenia with bone marrow failure, variable congenital malformations and predisposition to develop hematological or solid tumors. "BRIP1 and FANCC belong to the Fanconi anemia pathway while MDC1 and TP53BP1 are conserved DNA damage response genes." (PMID 34220964, 2021).
bladder cancer (5 papers, 2016 to 2022). "Methylation of the tumor suppressor gene TP53BP1, whose product mediates DNA damage response, was associated with GMD expression in COAD/READ, bladder cancer, and SCLC." (PMID 33676569, 2021).
colon carcinoma (4 papers, 2020 to 2023). "GO enrichment analysis showed that specific proteins, including TGFβ1, adenomatous polyposis coli (APC), CTNB1, low-density lipoprotein receptor-related protein (LRP) 5 (LRP5), LRP6, JAK1, ST14, and TP53BP1, were hypothetical CD151-interacting proteins in colon cancer." (PMID 33767593, 2021).
gastric cancer (4 papers, 2016 to 2023). A primary or metastatic malignant neoplasm involving the stomach. "We detected increased expression of FANCD2, TP53BP1, and RPA2 in early gastric cancer, suggesting that DNA damage and DDR are prevalent in the course of this disease." (PMID 36061145, 2022). "The expression of TP53BP1 positively correlated with the expression of cGAS, STING, and IRF3, while the expression of FANCD2 positively correlated with the expression of IRF3 and STAT6, suggesting the major role of DDR in SASP activation in early gastric cancers." (PMID 36061145, 2022).
hepatocellular carcinoma (4 papers, 2021 to 2024). A malignant tumor that arises from hepatocytes. "As an autophagy-related lncRNA, PLBD1-AS1 has been demonstrated to be significantly correlated with the prognosis of hepatocellular carcinoma and may be linked to TP53BP1 and CHMP4B." (PMID 37470034, 2023).
non-small cell lung carcinoma (4 papers, 2013 to 2024). A group of at least three distinct histological types of lung cancer, including non-small cell squamous cell carcinoma, adenocarcinoma, and large cell carcinoma.
lymph node metastasis (3 papers, 2019 to 2024). "The levels of TP53BP1 were significantly higher in tumor samples from patients without lymph node metastasis compared to those with lymph node metastasis." (PMID 34884985, 2021).
skin cancer (3 papers, 2011 to 2019). "However, certain mutations in TP53BP1 can also be associated to various cancers, more precisely to breast and skin cancers." (PMID 30857266, 2019).
follicular adenomas (2 papers, 2018 to 2022). "Unstable expression of TP53BP1 is associated with genomic instability in oncocytic follicular adenoma of thyroid." (PMID 29504908, 2018).
angiosarcoma (1 paper, 2023). A malignant tumor arising from the endothelial cells of the blood vessels. "EME1, FANCA, RAD51, TP53BP1, RAD51C, RPA1, and XRCC2 exhibited alterations in more than half the cases of the angiosarcoma cohort." (PMID 36779660, 2023).
dysferlinopathy (1 paper, 2023). "Analysis of muscle transcripts from patients with dysferlinopathy identified 6 downregulated DEGs (RFC4, RFC5, ATAD5, TP53BP1, WDR48, and RAD17) related to the cellular response to DNA damage stimulus." (PMID 38125829, 2023).
dyslipidemia (1 paper, 2024).
HIV-1 infection (1 paper, 2015). The type species of lentivirus and the etiologic agent of acquired immunodeficiency syndrome (AIDS).
metastatic prostate carcinoma (1 paper, 2024). A carcinoma that arises from the prostate gland and has spread to other anatomic sites.
retinoblastoma (1 paper, 2013). A malignant tumor that originates in the nuclear layer of the retina. "First, we used a tissue microarray to analyze the expression pattern of TP53BP1 on 90 primary human retinoblastomas and found that a subset of primary human retinoblastomas had elevated endogenous levels of TP53BP1 nuclear foci (Sup." (PMID 23765217, 2013). "TP53BP1 expression on 3 of each of the mouse retinoblastoma models was also analyzed and we found extensive endogenous levels of TP53BP1 nuclear foci in 100% of the samples analyzed (data not shown)." (PMID 23765217, 2013). "To complement the comet assays, we analyzed the focal accumulation and resolution of proteins that target dsDNA breaks (γ-H2AX and TP53BP1) in human and mouse retinoblastoma cells." (PMID 23765217, 2013). "Next, we analyzed the resolution of dsDNA breaks (γ-H2AX and TP53BP1 foci) in human and mouse retinoblastoma cells following exposure to 5 Gy IR." (PMID 23765217, 2013). "However, all mouse retinoblastoma cells displayed a significant reduction in their ability to resolve TP53BP1 foci over 24 hours, though p53TKO doesn't reach statistical significance (p=0.2)." (PMID 23765217, 2013).